EGFR (epidermal growth factor receptor)
Diseases named in the same sentence as EGFR in open-access papers (continued):
Sharing a sentence is not in itself a finding about the gene and the disease.
tumor (continued). "An antibody or an aptamer against the epidermal growth factor receptor (EGFR) was conjugated to the micelle surface to achieve tumor-targeting capacity." (PMID 39339195, 2024). "Given the mixed results of the dual-targeting approach with GE11, future research should explore alternative EGFR-specific peptides to enhance dual-targeting effectiveness and improve tumor imaging." (PMID 39598465, 2024). "PD‐L1 expression can be induced by external stimuli, such as interferon‐γ produced by tumour cells, and intrinsic oncogenic pathways, such as STAT3 and activated EGFR mutations." (PMID 39113235, 2024). "HER3 overexpression and payload-mediated tumor suppression is independent to resistance mechanism to EGFR TKIs." (PMID 38632563, 2024). "Combining EGFR inhibitors with chemotherapy results in the inhibition of tumor-induced angiogenesis, promotion of tumor cell apoptosis, and tumor regression in xenograft models." (PMID 39273318, 2024). "The study also showed that combined anti-FGFR and EGFR therapy suppressed tumour growth more effectively and enhanced the efficacy of anti-immunotherapy for tumours." (PMID 40135140, 2024). "Immunostaining of β‐catenin, EGFR, and EpCAM confirmed that these proteins were highly expressed in the Nr2e3−/− tumor tissues at 24‐week and 48‐week time points." (PMID 38790135, 2024). "Key hub genes, such as PLK1, CDK1, and EGFR, emerge as crucial regulators of tumor proliferation, signal transduction, and immune response." (PMID 39457373, 2024). "We then used this model sensitivity to the EGFR inhibitor osimertinib across coexisting cell populations within the same tumor." (PMID 39061010, 2024). "Our study suggests that tenovin-3 is a potential anti-tumor agent for NSCLC patient with EGFR exon 19 deletion." (PMID 38561419, 2024). "EGFR is a cell surface tyrosine kinase fundamental in cell proliferation, angiogenesis, and metastasis—a factor in tumor growth." (PMID 38248333, 2024). "Cell surface molecules can be used as good targets for anti-tumor drugs, such as epidermal growth factor receptor (EGFR), PD-L1, and insulin-like growth factor 1, all of which have been successfully used in the clinical treatment of tumors." (PMID 38706907, 2024). "Conversely, in tumor samples the levels of EGFR and of the activating phosphorylation of p42/p44 mitogen-activated protein kinases at Thr202/Tyr204 (ERK1/2) were substantially higher compared to normal samples." (PMID 38379085, 2024). "EGFR plays a crucial role in the proliferation, survival, and transformation of cancer cells and has emerged as an important molecule for enhanced tumor targeting." (PMID 38276624, 2024). "KEGG analysis revealed that these genes were enriched in tumor pathways closely related to tumor pathways, including EGFR tyrosine kinase inhibitor resistance, PI3K-Akt signaling pathway, PD-L1 expression, and PD-1 checkpoint pathway." (PMID 38180753, 2024). "Studies also reveal that EGFR and its downstream pathways play a crucial role in regulating processes like epithelial-mesenchymal transformation, migration, and tumor invasion." (PMID 39738201, 2024). "At the same time, PAICS level were related to tumor metastasis, EGFR status and gender in NSCLC patients based on TCGA database (left), whereas uncorrelated with tumor metastasis, EGFR status and gender from microarray analysis (right)." (PMID 38463398, 2024). "Various drugs targeting EGFR, ALK, ROS1 mutations, and VEGF are being tested and used in the clinical setting after carefully tailoring the therapy to the patient’s specific tumor type." (PMID 39123371, 2024). "Here, we integrated single-cell RNA (scRNA) sequencing, bulk RNA sequencing, multiplexed immunofluorescence and flow cytometry data from pretreatment and post-resistant tumor samples of EGFR-mutant NSCLC patients received third-generation EGFR-TKIs." (PMID 39638994, 2024).
tumor (continued). "This heightened risk often necessitates the reduction or discontinuation of EGFR-TKI treatment during targeted therapy, ultimately leading to tumor progression." (PMID 39211774, 2024). "High TGF-β expression inhibits the infiltration and anti-tumor function of CD8+ T cells, contributing to the “cold” TME of EGFR-mutated tumors." (PMID 39004699, 2024). "Tumor spots from the S2_Col_R and S4_Col_Sig patients showed lower EGFR signaling, while FOXM1 displayed higher transcriptional activity in patient S6_Rec." (PMID 38200223, 2024). "More thorough analyses of SHP2 inhibitor treatment in KRAS- and EGFR-mutant NSCLC models revealed tumor-intrinsic CCL5/CXCL10 secretion." (PMID 38504984, 2024). "EGF levels were significantly elevated in HCC tissues, and the activation of EGF/EGFR signaling correlated with aggressive tumor characteristics and intrahepatic metastasis." (PMID 38816668, 2024). "Further investigations have demonstrated that exogenous overexpression of EGFR in tumor cells attenuates the suppression of glycolysis induced by kaempferol." (PMID 38730663, 2024). "EGFR and HER2 have long been implicated in tumour progression, and development of targeted therapies towards these components of the ErbB signalling cascade has been extensively explored in multiple tumour types, including OAC." (PMID 39395265, 2024). "EVs, which were decorated with ligands specific for EGFR, conjugated to phospholipid (DMPE)-PEG were reported to target EGFR-overexpressing tumor cells with increased cell specificity and prolonged circulation time." (PMID 38796692, 2024). "In our clinical observations, immunohistochemistry results revealed a positive correlation between tumor‐p‐Src or p‐Akt and pericyte‐IL32 levels in our EGFR‐mutated patient cohort." (PMID 39435643, 2024). "(2024), single-domain antibodies (sdAbs) were utilized to construct NKCEs targeting NKp30 to redirect NK cell cytotoxicity toward EGFR-expressing tumor cells." (PMID 39911822, 2024). "Its anti-tumor effects are primarily attributed to the inhibition of the EGFR signaling pathway and the induction of apoptotic cell death." (PMID 39519855, 2024). "Considering the role of EGFR in tumor angiogenesis, the potential implication of angiogenesis was analyzed using the HUVEC tube formation assay." (PMID 38686044, 2024). "Comparative immunohistochemistry was performed targeting Hsp70 and EGFR on respective tumor sections." (PMID 39406917, 2024). "By decreasing the amount of EGFR proteins on the cell membrane, curcumin reduces sensitivity to its ligands, thereby inhibiting tumor cell proliferation." (PMID 39519045, 2024). "In EGFR-mutated NSCLC cells, CD73 suppressed immune responses by inducing T regulatory cells (Tregs), and CD73 blockage inhibited tumor growth in an immune-competent murine model." (PMID 38398101, 2024). "TKIs in thyroid cancer typically target receptors such vascular endothelial growth factor receptors (VEGFR), epidermal growth factor receptors (EGFR), and other kinases involved in angiogenesis and tumor development." (PMID 38501105, 2024). "Of the 19 patients with brain involvement, 15 (79%) had EGFR tumours, and 4 had received previous brain radiotherapy." (PMID 38610927, 2024). "Altogether, these data indicated that TGF-β was upregulated in EGFR-mutated NSCLC compared with WT, and its expression showed a negative linear correlation with CD8+ T cell infiltration in the tumor area." (PMID 39004699, 2024). "EGFR-mutant patients with brain metastases achieved encouraging levels of tumor remission with this regimen (iORR: 38.5%, iDCR: 80.8%)." (PMID 38758372, 2024). "Several tumors harboring genomic alterations with US Food and Drug Administration-approved indications in other tumor types were found including NF1, PIK3CA, EGFR Exon 19/20 insertions, and BRAF V600E mutations." (PMID 39191445, 2024).
tumor (continued). "For a given specimen, pathogenic variants of BRAF, EGFR, KRAS, and NRAS were identified and the determined VAFs were correlated with the corresponding tissue tumor cellularity." (PMID 38397405, 2024). "STAT3 interacts with products such as IL-6 receptors and epidermal growth factor receptor, expressed via a receptor, and promotes growth differentiation of tumor cells while inhibiting tumor cell death." (PMID 39590337, 2024). "In this case, tumor biopsies showed the elimination of EGFR+ tumor cells and EGFR CAR-T cell infiltration." (PMID 36873868, 2023). "Bispecific NKCEs harboring NKp46‐directed sdAbs elicited efficient NK cell‐mediated killing of EGFR‐positive tumor cells." (PMID 36775946, 2023). "In the current study, CD27xEGFR was demonstrated to have high-affinity binding to EGFR on EGFR+ tumor cells and to CD27 on CD27+ T cells." (PMID 37545491, 2023). "The acquired osimertinib resistance is highly variable, covering EGFR-dependent as well as EGFR-independent mechanisms, as a result of the high degree of tumor heterogeneity and adaptive cellular signaling pathways in NSCLC." (PMID 36831009, 2023). "For example, the epidermal growth factor receptor (EGFR) is highly expressed on the surface of tumor cells." (PMID 37842166, 2023). "Patients with high levels of EGFR have increased tumor invasion and lower total resection than those with low levels of EGFR expression." (PMID 37446128, 2023). "Among these core targets, EGFR was well known for its activity closely related to tumor growth, invasion, and metastasis." (PMID 37379130, 2023). "The tumor cells within GLICOs were shown to retain the key genetic features of parental tumors, such as EGFR amplification." (PMID 38596241, 2023). "Next, examination of the tumor cell membranes, using WB analysis after nanoparticle encapsulation, detected the proteins EGFR and CD47, specific for OCM and PLM, on the hybrid membrane and [Dbait-ADM@ZIF-8]OPM." (PMID 36873373, 2023). "In a study by Pectasides and colleagues, genomic tissue profiling identified discordance of common alterations (HER2, MYC, CCND1, EGFR) between primary tumor and metastasis in 32% of patients." (PMID 35834132, 2023). "What’s more, it’s also researched that tumor-suppressive activity in OS is correlative with the downregulation of EGFR." (PMID 37870753, 2023). "Osimertinib, a potent EGFR inhibitor, competitively binds to the ATP site of the tyrosine kinase domain of EGFR, inhibits EGFR autophosphorylation, blocks the cell cycle and promotes apoptosis of tumor cells." (PMID 36744262, 2023). "Loss of EGFR or ERBB2 in human Panc‐1 cells results in delayed migration, reduced proliferation rate, and increased tumor growth behavior." (PMID 37341059, 2023). "The required level of tumour cell EGFR positivity, CAR T-cell dosing/re-dosing and conditioning chemotherapy were all similar to those in the biliary cancer study." (PMID 36829563, 2023). "The decrease of VEGFA, TGFβ1 and EGFR upon anti-PD-L1 treatment in PD-L1 low tumor cells provides a rationale for the use of those antibodies in PD-L1 low tumors." (PMID 38152616, 2023). "Both afatinib and osimertinib treatments exhibit favorable tumor responses and PFS benefits in patients with NSCLC who carry uncommon EGFR mutations." (PMID 37116899, 2023). "Upon removal of the drug, colonies that grew from the DTPs were again sensitive to the EGFR inhibitor, showcasing the innate ability of tumor cells to temporarily adapt to the onslaught of a drug such that the entire population is not eradicated." (PMID 37779896, 2023). "The signaling pathway driven by EGF/EGFR is an important regulator of tumor growth, invasion and metastasis in epithelial malignancies." (PMID 36960065, 2023).
tumor (continued). "Activation of the EGFR pathway increases the production of tumor-derived VEGF that acts on endothelial cells in a paracrine manner to promote angiogenesis." (PMID 36872336, 2023). "A clinical study reported that patients who received EGFR-TKIs had alteration in their tumor microenvironment that contributed to immunotherapy." (PMID 37869096, 2023). "The EGFR signal pathway has been shown to perform a critical role when tumor cells acquire anoikis resistance in peripheral blood, followed by metastasis." (PMID 37345046, 2023). "One of the common features of tumor cells is the high expression of epidermal growth factor receptor (EGFR) on their surface to promote proliferation." (PMID 37686050, 2023). "Initial functional analyses for the generated VHH‐based NKCEs were conducted using the EGFR‐overexpressing tumor cell line A431 as well as NK cells derived from PBMCs of four healthy donors." (PMID 36775946, 2023). "In the present study, we have demonstratedtwo different sensingplatforms that employ antigen-conjugated nucleic acid strands forthe detection of a bispecific antibody against the tumor-related proteinsMucin1 and EGFR." (PMID 37856082, 2023). "Collectively, our data showed that IL1RL1+ Treg cells coupled with CAFs via an AREG/EGFR axis to promote tumor immunosuppression." (PMID 37611111, 2023). "This genetic abnormality is related to tumor vascularity and grade, while increased tumor perfusion is predictive of EGFR amplification." (PMID 37074422, 2023). "All patients who expressed EGFR transcripts in their peripheral blood were found to express the EGFR protein in their primary tumor." (PMID 36675253, 2023). "Afatinib can control tumor progression and improve the prognosis of EGFR mutant NSCLC patients with brain metastasis." (PMID 37228701, 2023). "Animal study data further showed that inhibition of ILT4 alone repressed tumor progression and immune evasion in EGFR mutant NSCLC." (PMID 36874015, 2023). "In NSCLC cells, the VEGF/VEGFR pathway shares common downstream signaling with EGFR, indicating its additional role in supporting tumor growth when EGFR is blocked." (PMID 37800802, 2023). "In this regard, they discovered that one tumor clone exhibited EGFR, CDK6, and MET amplification, whereas another subclone received a copy of chromosome 3 with PIK3CA, resulting in PIK3CA amplification." (PMID 37762559, 2023). "Among 38 patients who underwent PD-L1 immunohistochemical testing after developing EGFR-TKI resistance, we also explored changes in PD-L1 expression in tumor cells between before receiving EGFR-TKI treatment and the development of drug resistance." (PMID 37266427, 2023). "All patients had EGFR 20ins documented by local testing at enrollment, 143 of whom (95.3%) were further confirmed by central testing on tumor tissue samples (n = 143) and/or paired peripheral blood samples (n = 117)." (PMID 37308490, 2023). "This targeted nanocarrier provided potential therapeutics to control tumor growth in drug-resistant TNBC via EGFR targeting and also exhibited controlled release, and prevent transporter efflux which helps the drug to be bioavailable at the tumor site." (PMID 36678877, 2023). "The EGFR-positive status of the tumor often correlates with poor prognosis and outcome, as it is beneficial for cancer cell proliferation." (PMID 38201251, 2023). "Univariate screening determined the patient’s age, sex, smoking history, tumor family history, disease, ECoG score, and type of EGFR change (only exon 19 was removed and L858R was identified)." (PMID 37791062, 2023). "For example, PI3K/mTOR, PI3K/HDAC, PI3K/AKT/mTOR, and PDGFR/PI3K/EGFR/VEGFR2 multi-target inhibitors were developed with the hope of effectively improving anti-tumour activity." (PMID 37489050, 2023). "Out of the 26 tumor specimens, 16 (61.5%) expressed low total-EGFR and 10 (38.5%) expressed high total-EGFR." (PMID 36702855, 2023).
tumor (continued). "A tumour cell threshold of ≥10% is most commonly used among the laboratories (22/50, 44.0%) for evaluating the EGFR status with a single-gene testing approach." (PMID 37713929, 2023). "The EGFR-HIF1a signaling pathway is known to promote angiogenesis and invasion, leading to enhanced tumor activity in NSCLC." (PMID 37719531, 2023). "Adjuvant therapy in EGFR mutated NSCLC, as well as preoperative immunotherapy in early stages, was associated with fewer relapses or post-operative tumor progression." (PMID 37568927, 2023). "The epidermal growth factor receptor (EGFR) is one of the main tumor drivers and is an important therapeutic target for many cancers." (PMID 37442828, 2023). "Using animal models, we obtained a significant anti-tumor effect when we recently used ‘off-the-shelf’ human EGFR-CAR-NK cells and human PSCA-CAR-s15NK cells to treat solid tumors (e.g., glioma and pancreatic cancer)." (PMID 37131214, 2023). "EGFR has also been observed in tumor cell nuclei in OSSN lesions, showing the nuclear translocation and activation status of this receptor." (PMID 37055797, 2023). "Some studies have confirmed that adherent tumours with GGO on imaging are prone to EGFR mutation, and the EGFR mutation rate tends to be related to the volume percentage of GGO, that is, the proportion of GGO in the lesion." (PMID 37340599, 2023). "The first immunotherapeutic drug to be evaluated was Cetuximab, which targeted the epidermal growth factor receptor (EGFR) pathway, a pathway vital for tumour cell survival and proliferation." (PMID 37514031, 2023). "The clinical parameters of gender, smoking history, nodule type, CEA, SCC-Ag, clinical stage, tumor long axis, and tumor short axis explained the differences between EGFR mutant and wild-type patients (all p < 0.05 in training set)." (PMID 37014500, 2023). "It has been demonstrated that sodium orthovanadate (vanadate) through the epidermal growth factor receptor (EGFR) pathway can overcome tumor resistance to these viruses and improve the antitumor effects of RNA‐based oncolytic viruses in a synergistic fashion." (PMID 36618103, 2023). "Specifically, PGRMC1 dimerizes in a heme-dependent manner and subsequently binds to EGFR, thereby enhancing tumour aggressiveness." (PMID 37887342, 2023). "Abnormal expression and activation of EGFR which belongs to the tyrosine kinase family, can lead to chemotherapy resistance of tumor cells." (PMID 37584258, 2023). "The deregulation of this pathway can induce increased cell proliferation, the inhibition of apoptosis, the stimulation of angiogenesis, the promotion of tumor invasion/metastasis, and resistance to treatments such as anti-EGFR monoclonal antibodies." (PMID 38136368, 2023). "In xenograft tumor tissues, EGFR overexpression promoted the radiation therapy response in HPV-positive HNSCC by attenuating DNA damage repair and HPV E6 decrease." (PMID 36646686, 2023). "Paired tumor tissues from ten patients before EGFR-TKIs treatment and after acquiring resistance to EGFR-TKIs (gefitinib or erlotinib) were obtained." (PMID 37735252, 2023). "Discordances between CTCs and tissue biopsy, as seen here in patients with HER2+ CTCs and EGFR+ CTCs, offer opportunities to explore alternative therapies as CTCs better represent the metastatic scenario than tumor tissue." (PMID 36900406, 2023). "In the clinical samples, the infiltration levels of T cell CD8+ and NK cells in the tumor parenchyma of EGFR-mutant LUAD was lower in the MMP11-positive than in the MMP11-negative group." (PMID 36756152, 2023). "This hints towards tumour subtype-specific interactions and alternative mechanisms to acquire EGFR inhibitor resistance." (PMID 37666855, 2023).